MYBL1 (MYB proto-oncogene like 1)
Diseases named in the same sentence as MYBL1 in open-access papers (continued):
Sharing a sentence is not in itself a finding about the gene and the disease.
B-cell lymphoma (2 papers, 2015 to 2022). "It was also suggested that MYBL1 rescues murine B-cell lymphoma cells form the growth arrest and apoptosis induced by anti-immunoglobulin M (IgM) antibody through maintaining c-Myc expression." (PMID 35681031, 2022). "The regulation of Mybl1 to c-myc was confirmed in murine B-cell lymphoma and was hypothesized to override the proapoptotic program of GC B-cells, thereby promoting malignant transformation." (PMID 25940947, 2015).
pancreatic cancer (2 papers, 2022 to 2025). "More importantly, the positive correlation observed between MYBL1 and ANGPT2 expression was not only confirmed in a cohort of human HCC specimens, but also in several published datasets such as pancreatic cancer, gastric cancer, and stomach adenocarcinoma." (PMID 35987690, 2022). "Importantly, we found that the HDAC4/MybL1/YAP pathway is also present in colon and prostate cancer cells, consistent with our observations in pancreatic cancer cells." (PMID 41281751, 2025).
Sepsis (2 papers, 2017 to 2021). Sepsis is defined as life-threatening organ dysfunction caused by a dysregulated host response to infection. "Through the bioinformatics analysis, we found that MSC-derived exosomes exerted the cardio-protection in sepsis through regulating miR-146a-5p and miR-146a-5p further protected the cardiomyocyte through regulating MYBL1." (PMID 34691188, 2021). "In this study, ROC analysis results further indicate that the four hub genes (MYBL1, KLRG1, STOM and MS4A4A) had good diagnostic performance in sepsis, close to that of genes previously reported." (PMID 29237456, 2017). "Among those novel hub genes, we assessed the expression patterns of MYBL1, KLRG1, STOM and MS4A4A from the top 2 sepsis-associated modules (module “midnight blue” and module “cyan”) by qPCR." (PMID 29237456, 2017). "However, the role of MYBL1 in sepsis-induced cardiac dysfunction and inflammatory response is rarely reported." (PMID 34691188, 2021). "Both the qPCR results and ROC analysis results suggest that the four hub genes (MYBL1, KLRG1, STOM and MS4A4A) could be novel diagnostic biomarkers for pediatric sepsis." (PMID 29237456, 2017). "Therefore, upregulation of MYBL1 could promote the progression of sepsis inhibited by miR-146a-5p mimics in vitro." (PMID 34691188, 2021). "qPCR results suggest hub genes (MYBL1, KLRG1, STOM and MS4A4A) in the candidate modules as promising potential transcriptomic markers for pediatric sepsis diagnosis." (PMID 29237456, 2017). "The expression levels of MYBL1 and KLRG1 in the sepsis group were significantly lower than those of the control group (P < 0.001 respectively)." (PMID 29237456, 2017).
triple-negative breast carcinoma (2 papers, 2024). An invasive breast carcinoma which is negative for expression of estrogen receptor (ER), progesterone receptor (PR), and human epidermal growth factor receptor 2 (HER2). "Related to cancers, the MYBL1 gene is over-expressed in low-grade gliomas, dysregulated in breast adenoid cystic carcinomas (a rare triple negative breast cancer (TNBC)) and salivary gland carcinomas where gene-fusion mutations with ACTN1 and NFIB genes are identified." (PMID 39796135, 2024). "Previous data show MYBL1 overexpressed in triple-negative breast cancer (TNBC)." (PMID 38473786, 2024). "In addition, MYBL1 and VCPIP1 genes are co-expressed and dysregulated in some of the same triple negative breast cancer patient samples." (PMID 39796135, 2024).
acinic cell carcinoma (1 paper, 2023). "Several genes that are known to be important in ACC tumors are highlighted with black dots at right, including (from top to bottom) EN1, GABRP, MYB, MYBL1 and NFIB, all of which are expressed more highly in the ACC tumors than in the normal salivary gland or acinic cell carcinoma samples (at left)." (PMID 36900183, 2023).
atherosclerosis (1 paper, 2024). A disease characterized by the build-up of fatty material and calcium deposition in the arterial wall resulting in partial or complete occlusion of the arterial lumen. "Our study aims to clarify the mechanism of MYBL1 in endothelial cells involved in atherosclerosis by regulating PLEKHM1-induced autophagy, and to provide new understanding of atherosclerosis." (PMID 38797732, 2024). "RNA-seq, Western blot, qRT-PCR, Luciferase reporter system, Immunofluorescence, Flow cytometry, ChIP and CO-IP were used to study the role and mechanism of MYBL1 in atherosclerosis." (PMID 38797732, 2024). "The aim of this study is to elucidate the role and mechanism of MYBL1 in atherosclerosis." (PMID 38797732, 2024). "However, there are few studies on the role of MYBL1 in atherosclerosis." (PMID 38797732, 2024). "The mechanism of how MYBL1 downregulation leads to atherosclerosis remains unknown." (PMID 38797732, 2024). "MYBL1 knockdown in HUVECs was involved in atherosclerosis by inhibiting PLEKHM1-induced autophagy, which provided a novel target of therapy for atherosclerosis." (PMID 38797732, 2024). "Mechanistic studies showed that MYBL1 knockdown inhibited autophagosome and lysosomal fusion in HUVECs by inhibiting PLEKHM1, thereby exacerbating atherosclerosis." (PMID 38797732, 2024). "Firstly, heatmap analysis of the three differential genes including MYBL1, ARHGAP30 and FAM20A were performed and found that MYBL1 had the highest expression in early atherosclerotic tissues and the lowest expression in advanced atherosclerosis, while FAM20A and ARHGAP30 had the opposite trend." (PMID 38797732, 2024). "However, there is no systematic study on the role of MYBL1 in atherosclerosis." (PMID 38797732, 2024).
Breast Invasive Carcinoma (1 paper, 2024). "In part two, we identify and validate expression and gene-related alterations of MYBL1, VCIP1, MYC and BOP1 genes in TNBC cell lines and patient samples selected from the Breast Invasive Carcinoma TCGA 2015 dataset available at cBioPortal.org." (PMID 38473786, 2024).
chordoma (1 paper, 2022). Chordomas are rare malignant tumors arising from embryonic remnants of the notochord in axial skeleton. "Other regulators of stemness, such as MYBL1 and RECK are also predicted targets for multiple upregulated miRNAs in our study, and, together with LCOR and YAP/TAZ may form a regulatory network maintaining the stem-cell phenotype in chordoma." (PMID 36033338, 2022).
cortical dysplasia (1 paper, 2025). "Interestingly, LEATs other than PLNTY, including ganglioglioma, DNET, and MYB- or MYBL1-altered pLGGs, also frequently coexist with regional cortical dysplasia." (PMID 40668344, 2025).
diabetes (1 paper, 2024). "Although Wnt10 and Lin37 are not directly related to the occurrence of diabetes and morbid obesity, the results of the PPI network analysis showed that these genes directly interact with genes associated with the development of T2DM, such as Mybl1." (PMID 38396669, 2024).
diffuse large B-cell lymphoma (1 paper, 2010). "LMO2, MYBL1, BCL6, LRMP, and CCND2 in our 35 signature genes were also reported in Lossos's 36 genes, which predicted survival in diffuse large-B-cell lymphoma." (PMID 20856936, 2010).
Fanconi anemia (1 paper, 2022). Fanconi anemia (FA) is a hereditary DNA repair disorder characterized by progressive pancytopenia with bone marrow failure, variable congenital malformations and predisposition to develop hematological or solid tumors. "Moreover, the results of the ssGSEA algorithm indicated that MYBL1 was positively correlated with most immune terms, especially base excision repair, fanconi anemia pathway, and homologous recombination; MYBL1 was negatively correlated with most metabolism terms." (PMID 36591240, 2022).
Infertility (1 paper, 2012). "Moreover, Mybl1 was independently identified recently in an unbiased mutagenesis screen for infertility phenotypes involving meiotic arrest." (PMID 23028291, 2012).
liver cancer (1 paper, 2019). An epithelial or non-epithelial malignant neoplasm that arises from the liver. "Thus, miR-221 was suggested to negatively control MYBL1 in liver cancer, based on the miR-221-dependent downregulation of relative luciferase activity by the MYBL1 3′UTR27, and RNA-seq analysis in MCF-7 cells also indicated downregulation of MYB and MYBL1 by miR-221/22246." (PMID 30833639, 2019).
morbid obesity (1 paper, 2024). An excess of body weight, normally defined as an individual with a body mass index greater than 35 or a body weight greater than one hundred percent of ideal body weight. "Most of these genes, such as transcription factor family genes Mybl1 and Fnip2, are related to the occurrence and development of T2DM and morbid obesity." (PMID 38396669, 2024).
renal carcinoma (1 paper, 2022). A carcinoma arising from the epithelium of the renal parenchyma or the renal pelvis. "Moreover, based on the immunohistochemical result from the HPA database, a higher protein level of MYBL1 in renal cancer tissue was observed." (PMID 36591240, 2022).
salivary gland cancer (1 paper, 2024). A primary or metastatic malignant neoplasm that affects the major or minor salivary glands. "Salivary gland cancer organoids recapitulated the parental tissue genotypic characterization, with >97.6% of all COSMIC annotated variants and all MYB, MYBL1, and NFIB gene rearrangements retained." (PMID 39309690, 2024).
tumor (49 papers, 2013 to 2026). "Similar to what we observed for the MYBL1 gene, exons 14 and 16 of the Tenascin-C gene are considered tumor-associated regions of the gene that affect invasive properties of the gene in breast cell lines." (PMID 39796135, 2024). "Variants detected by NGS considered inconsistent with WHO tumor type predominantly occurred as BRAF or MYBL1 alterations in HGG defined by WHO criteria (8/14)." (PMID 36928815, 2023). "We are classifying this unique MYBL1 exon as a tumor-associated exon." (PMID 39796135, 2024). "However, the clinical significance and molecular mechanisms of MYBL1 underlying tumor angiogenesis and sorafenib resistance in cancer remain elusive." (PMID 35987690, 2022). "Strategies based on detection of newly described genetic events (such as MYB activating super-enhancer translocations and alterations affecting another member of MYB transcription factor family-MYBL1) offer new hope for improved risk assessment, therapeutic intervention and tumor surveillance." (PMID 27533466, 2016). "Notably, high MYBL1 levels were associated with poor prognosis in HCC patients, and MYBL1 was identified as a promotor of tumor angiogenesis and sorafenib resistance in HCC cells stably expressing MYBL1 (HepG2-MYBL1 cells) by activation of angiopoietin 2 (ANGPT2)." (PMID 38835346, 2024). "Knockdown of MYBL1 or overexpression of AIF1L exhibited synergistic anti-tumour effects when combined with PD-1 blockade." (PMID 41772383, 2026). "For a definitive diagnosis, the tumor must be IDH-wild type and H3-wild type, and should exhibit a structural variant involving either the MYB or MYBL1 gene." (PMID 40861626, 2025). "The most notable differences in gene expression associated with miRNA-221 between non-tumor hepatocytes and viral-induced HCC involved NTF-3 and MYBL1 genes." (PMID 39408891, 2024). "NTF-3 was considered to have significantly lower expression in HCC tissue than in non-tumor hepatocytes, while the MYBL1 gene was observed to be significantly overexpressed in tumor tissue when compared with non-tumor hepatocytes using in silico analysis." (PMID 39408891, 2024). "With co-operation with c-MYC, the MYBL1 gene can rescue human B-cell neoplasia from apoptosis, aiding in tumor progression." (PMID 39796135, 2024). "Because the gene is a strong transcriptional activator and involved in many of the events key to tumor progression, we knocked down MYBL1 in MDA-MB-231 cells and identified MYBL1 gene partners either directly or indirectly affected by the process." (PMID 39796135, 2024). "Prior functional genomics work showed that the truncated MYBL1 protein expression induced tumor formation in nude mice, supporting the notion that truncated MYB(L1) genes are a potential driver of these tumors." (PMID 39422766, 2024). "Numerous studies have demonstrated that MYBL1 is highly expressed in many cancers and involved in malignant development of tumor." (PMID 35987690, 2022). "Our study provides new knowledge about the prevalence and clinical significance of MYB/MYBL1 alterations and indicates the presence of genes with tumor suppressive functions in 6q23.3-qter that contribute to poor prognosis and short overall survival in ACC." (PMID 35954356, 2022). "Based on the correlation analysis between MYBL1 and EV density, we next studied the biological function of MYBL1 in regulating tumor angiogenesis." (PMID 35987690, 2022). "According to the GTEx and TCGA data, MYBL1 all showed a higher expression level in ccRCC tumor tissue compared with the control normal tissue." (PMID 36591240, 2022). "Our result indicated that MYBL1 is a novel biomarker of ccRCC, which can remodel the tumor microenvironment, affect immunotherapy response and guide precision medicine in ccRCC." (PMID 36591240, 2022). "Our results again emphasize the importance of MYB/MYBL1 gene fusions in AdCC tumor biology and their specificity to AdCC." (PMID 36077692, 2022).
tumor (continued). "Our study provides new knowledge about the frequency and clinical significance of MYB/MYBL1 alterations and identifies genes with tumor suppressive functions on chromosome 6 that contribute to poor prognosis in ACC." (PMID 35954356, 2022). "MYB protooncogene-like 1(MYBL1), located on chromosome 8q13.1, is a novel tumor-related gene and a strong activator of transcription." (PMID 34691188, 2021). "However, the trend is changing, and data documenting the MYBL1 gene’s involvement in tumor progression are increasing." (PMID 38473786, 2024). "The mechanisms leading to the upregulated NTF-3 and MYBL1 expression in tumor tissue of one organ or downregulated expression in tumor tissue of another organ are still unknown." (PMID 39408891, 2024). "The transcriptional regulation of VCPIP1 by the MYBL1 gene could implicate MYBL1 in these processes, which might contribute to tumor processes in TNBC." (PMID 39796135, 2024). "The tumor belongs to the family of MYB/MYBL1-altered gliomas and is an IDH-wild type." (PMID 37920791, 2023). "Herein, our study demonstrates that MYBL1 is overexpressed and correlates with tumor microvascular density and with distant metastasis in HCC, suggesting that upregulation of MYBL1 might contribute to the malignant potential of HCC." (PMID 35987690, 2022). "Furthermore, the tumor formed by HepG2/MYBL1 cells were larger, in both size and weight than the control tumors." (PMID 35987690, 2022). "Furthermore, the biological role of MYBL1 in HCC angiogenesis was further examined via using an in vivo tumor model." (PMID 35987690, 2022). "We examined whether MYBL1-induced tumor angiogenesis is involved in the regulation of sorafenib resistance in HCC cells." (PMID 35987690, 2022). "In addition, our results show that MYBL2 and MYBL1 genes are also involved in the activation of the EMT pathway to promote tumor metastasis, which has also been confirmed in some tumors." (PMID 35664326, 2022). "Copy‐number analysis revealed genomic events involving MYBL1 in four tumours and MYB in one tumour." (PMID 35836307, 2022). "An MYB-NFIB and MYB-split-positive status had no or only a weak clinicopathological impact whereas an MYB/MYBL1-split-positive status was associated with a higher tumor grade and a local aggressiveness of the tumor but failed to have a prognostic impact." (PMID 29682203, 2018). "Data suggest MYB is a tumor suppressor while it might be that MYBL1 is involved in tumor progression." (PMID 28966727, 2017). "Hence, understanding the interplay between NTF-3-mediated signaling and MYBL1 activity could provide insights into their collective impact on tumor development and progression." (PMID 39408891, 2024). "Furthermore, some studies suggested that Mybl-1 was an apoptosis suppressor in tumor cells." (PMID 36497007, 2022). "In vivo assay showed that the inhibition of MYBL1 could also hamper tumor growth in mice." (PMID 36591240, 2022). "Similar to MYB- or MYBL1-altered pLGGs, DLGG-MAPK tumors are expected to display consistent imaging characteristics throughout the tumor, potentially allowing radiologists to identify characteristic features macroscopically on MRI." (PMID 40668344, 2025). "RNA sequencing identified the oncogenic fusion MYB/MYBL1::QKI, a known driver of this tumour subtype." (PMID 41033792, 2025). "MYBL1, VCPIP1, MYC and BOP1 transcript expression levels were assessed in MCF10A non-tumor triple negative cell lines compared to Hs 578T, BT-549 and MDA-MB-231 TNBC cell lines." (PMID 38473786, 2024). "Studies show MYBL1 (which is located at chromosome 8q13.1) binds to and activates the ANGPT1 gene (which is located at chromosome 8q23.1) to promote tumor angiogenesis in hepatocellular carcinoma." (PMID 38473786, 2024). "As a family, the c-MYB, MYBL1 and MYBL2 genes are involved in cell proliferation, differentiation, apoptosis, and tumor transformation processes." (PMID 39796135, 2024).